RNU1-101P (RNA, U1 small nuclear 101, pseudogene)
Gene: Small nuclear RNA gene on chromosome 8 (70,077,906 to 70,078,032, reverse strand). Ensembl gene ENSG00000212473.
Homologues: Orthologues: chimpanzee U1 (96% identical), macaque U1 (96% identical), mouse Gm23735 (56% identical), rat U1 (49% identical). Paralogues in human: RNU1-1 (84% identical), RNU1-2 (84% identical), RNU1-27P (84% identical), RNU1-28P (84% identical), RNU1-3 (84% identical), RNU1-4 (84% identical), RNU1-89P (84% identical), RNVU1-18 (84% identical), RNVU1-29 (84% identical), RNVU1-31 (84% identical), RNVU1-7 (84% identical), U1 (84% identical), and 133 more.